LRP1B (LDL receptor related protein 1B)
Diseases named in the same sentence as LRP1B in open-access papers (continued):
Sharing a sentence is not in itself a finding about the gene and the disease.
cancer (162 papers, 2010 to 2026). A tumor composed of atypical neoplastic, often pleomorphic cells that invade other tissues. "Among them, LRP1B, a potential tumor suppressor gene, has been shown to enhance responses to immune checkpoint inhibitors (ICIs) in cancers with mutations in this gene." (PMID 40492126, 2025). "LRP1B has been found to be associated with improved outcomes in multiple cancer types, including NSCLC, with ICB treatment." (PMID 40011914, 2025). "•Mutations in the LRP1B gene can affect immune cell infiltration in cancer patients, thereby affecting the effect of clinical immunotherapy." (PMID 39532036, 2024). "In this study, we selected three LRP1B gene polymorphisms (rs10496915, rs431809, and rs6742944) to compare their allelic distributions among cancer-free subjects, patients with OSCC, and OSCC patients with DM." (PMID 38612772, 2024). "LRP1B has been emerged as a a potential therapy target and associated with cancer responses to immune checkpoint inhibitor therapies." (PMID 37077919, 2023). "The collected data regarding the differentially expressed proteins (DEPs) following LRP1B silencing, along with their associated pathways, offer new insights into the functional role of LRP1B in cancer cells." (PMID 37511044, 2023). "A recent study showed that patients with cancer who had LRP1B mutations had improved clinical outcomes when receiving immune checkpoint inhibitors." (PMID 37427142, 2023). "Of particular note, LRP1B mutation has been shown to be a positive predictor of response to immune checkpoint inhibitor therapy in multiple human cancer subtypes." (PMID 37079639, 2023). "Lrp1b has been mainly implicated in roles in the cell cycle, cellular growth regulation, and proliferation in the context of cancer, similarly to Lrp11, which has been related to oncogenesis and the stress response." (PMID 36648592, 2023). "This holds particular relevance for genes such as LRP1B, whose deletion/mutations, although not fully understood, have been associated with cancer patients’ prognosis and response to therapy." (PMID 37511044, 2023). "Mutations in TET2, PTPRT, and LRP1B are associated with favorable responses to ICIs in other cancer types." (PMID 37654198, 2023). "We observed other frequently-mutated genes in AS-HN including CSMD3, MUC16, and LRP1B, which are known cancer-related genes." (PMID 37106027, 2023). "LRP1B is a member of the low-density lipoprotein receptor-related protein family and is associated with metabolic stress in cancer." (PMID 35887658, 2022). "These genes include ARID1A, a tumor suppressor and chromatin regulator and LRP1B, which encodes a low-density lipoprotein receptor-related protein that is frequently mutated in cancers." (PMID 35557512, 2022). "Since LRP1B has attracted more and more attention in the cancer research currently, a more comprehensive approach to build an LRP1B mutation-associated prognostic model for HCC is required." (PMID 34386813, 2021). "LRP1B mutations, as an important cancer suppressor gene 45, are correlated with higher-TMB and neoantigen burden." (PMID 33976731, 2021). "Cancer survival analysis demonstrated that samples with LRP1B mutation showed poor disease outcomes in CC (P=0.013) and HNSCC (P=0.0124)." (PMID 33994859, 2021). "In EC, a research once has pointed that LRP1B possessed the recurrent copy-number variant character, significantly promoting cancer cell proliferation, migration, and invasion." (PMID 32454908, 2020). "Recently, LRP1B has been implicated in antigen presentation and as a regulator of inflammation and progression in cancer." (PMID 31164891, 2019). "Some studies reported that deregulations of the LRP1B gene are associated with resistance to chemotherapy and worse survival in cancer." (PMID 31336878, 2019). "RNF43 and LRP1B were among the genes, most commonly mutated in GC, lending support to the hypothesis that these genes are important for cancer development and/or progression." (PMID 36823311, 2023).
cancer (continued). "Moreover, there was evidence that the TMB showed a noticeable increase in cancer samples with LRP1B mutations compared to those with the wild‐type mutations, which was consistent with our results." (PMID 36282125, 2023). "Thus, both, RNF43 and LRP1B are among the most commonly mutated genes in GC underscoring their putative significance in cancer development and progression." (PMID 36823311, 2023). "The top intra-chromosome co-mutation was TTN:LRP1B, which occurred in 16 of 39 cancer types." (PMID 35053577, 2022). "Interestingly, a multicenter pan-cancer research showed that patients with LRP1B mutation had a better outcome with immunotherapy, independent of TMB status." (PMID 36686739, 2022). "Additionally, DDX27, MDM2, RNF40, MMS22L, CCNK and LRP1B were detected as missense mutational cancer gene." (PMID 34313788, 2021). "Furthermore, LRP1B mutation status was also found to be associated with higher mutation count in pan-cancer studies (P = 0.0206)." (PMID 33994859, 2021). "LRP1B mutation contribute to favorable response to immunotherapy across pan-cancer." (PMID 35186006, 2021). "MDM2 and LRP1B have recently been reported as mutational cancer drivers." (PMID 34313788, 2021). "Interestingly, human cancers carrying LRP1B mutations seem to increase their responsiveness to the immune checkpoint inhibitors." (PMID 34205480, 2021). "LRP1B expression has also been associated with cancer response to therapy." (PMID 34577535, 2021). "Our data on PDAC are in agreement with literature on other cancers, suggesting that LRP1B mutations may mark high-risk cancers prone to generalization on one side and suggest targeted therapy for those already generalized on the other side." (PMID 33255265, 2020). "LRP1B is one of the top ten genes mutated in human cancers and might be a potential contributor to the emergence of chemotherapy resistance." (PMID 32429941, 2020). "LRP1B is a very large gene, frequently mutated in human cancers." (PMID 33255265, 2020). "Interestingly, many novel cancer-associated genes identified by the excess of missense mutations are large genes with repetitive functional domains: LRP1B, CSMD3, FLG, USH2A and others." (PMID 30453881, 2018). "The deletion of LRP1B also has been associated with chemotherapy resistance in high-grade cancers." (PMID 29181411, 2017). "A comprehensive study across multiple cancer types demonstrated that patients with pathogenic or likely pathogenic LRP1B alterations experienced significantly improved outcomes with ICI treatment compared to those with alterations of unknown significance, regardless of their TMB/MSI status." (PMID 40492126, 2025). "In our datasets, the TMB rates in samples with LRP1B mutations tended to fall into the medium or high categories, and further analysis of 25 independent cancer types verified this outcome, thereby suggesting that LRP1B mutations may be a good biomarker for immune intervention." (PMID 36204371, 2022). "LRP1B mutations may also be associated with upregulation of inflammatory responses, consistent with a growing body of evidence that chronic inflammation predisposes to cancer formation." (PMID 27974047, 2016). "Our analysis identified numerous SIR-associated mutations in oncogenes (e.g., MECOM, NFATC2) and tumor suppressor genes (e.g., LRP1B, PTPRD), as well as in cancer-associated lncRNAs (e.g., MALAT1, NEAT1)." (PMID 41153425, 2025).
cancer (continued). "Although several studies have examined LRP1B’s role in various cancers, its involvement in HC and CAD remains underexplored." (PMID 39445733, 2025). "Although the functional role of LRP1B dysfunction is still unclear, numerous studies have demonstrated that epigenetic mechanisms can affect LRP1B inactivation in several types of cancers." (PMID 37727135, 2024). "Somatic disruption of the LRP1B gene has also been observed in several other cancer types, including lung, gastric, and squamous cancers." (PMID 38308491, 2024). "Patients with LRP1B mutations exhibit higher TMB scores and are associated with improved outcomes of cancer immunotherapy." (PMID 39193390, 2024). "Combining these findings from multiple studies indicates that LRP1B plays suppressive functions in the development of cancer and that regaining LRP1B function would be a viable approach to treating the disease." (PMID 38612772, 2024). "In order to examine the potential correlation between LRP1B gene polymorphisms and the onset of oral carcinogenesis, 311 patients with OSCC and 300 cancer-free controls were enrolled in this case–control study." (PMID 38612772, 2024). "In human cancer, low-density lipoprotein receptor-related protein 1B (LDL receptor related protein 1B; LRP1B) is one of the most frequently mutated genes." (PMID 38612772, 2024). "LRP1B encodes a member of the low density lipoprotein (LDL) receptor family, which has been implicated in both metabolic phenotypes and several cancers." (PMID 37345113, 2023). "On the one hand, the novel cellular tools developed in this study hold potential for advancing our understanding of the role of LRP1B in cancer." (PMID 37511044, 2023). "Over the years, and even with the increased knowledge brought by next-generation gene sequencing, the LRP1B gene remains one of the most frequently altered genes among different cancers." (PMID 37511044, 2023). "The evaluation of LRP1B alterations at a genetic level is yielding interesting results in terms of their impact on cancer patient prognosis and response to therapy." (PMID 37511044, 2023). "Still, important knowledge on LRP1B has been gathered mostly from studies carried out in cancer cell lines, either by partially re-establishing its expression (with mini-receptors) or by downregulating its expression through RNA interference." (PMID 37511044, 2023). "LRP1B was revealed to suppress the activation of IL-6-JAK-STAT3 by several cancer-related previous studies." (PMID 38019868, 2023). "While some studies have reported that LRP1B silencing with siRNA/shRNA results in increased proliferation, migration, and invasion in several cancer cell lines, others have shown that lentiviral CRISPR/Cas9 LRP1B knockdown inhibited cell growth in HCC cells." (PMID 37511044, 2023). "Here, we explored the potential of CRISPR/Cas9-mediated gene editing to silence LRP1B in cancer cells to gain a deeper insight into the functional role of LRP1B." (PMID 37511044, 2023). "LRP1B remains one of the most altered genes in cancer, although its relevance in cancer biology is still unclear." (PMID 37511044, 2023). "Overall, our study not only sheds light on the functional consequences of LRP1B alterations in GB but also paves the way for future investigations into its broader implications in cancer research and the development of innovative therapeutic approaches." (PMID 37511044, 2023).
cancer (continued). "In the second dataset, LUSC, PIK3CA (46.5%), EGFR (7%), PDE4DIP (6.6%), KRAS (4.4%), and RELN (4.4%) were labeled with copy number gain, while CDKN2A (27.9%), LRP1B (17.4%), PTEN (9.8%), and PTPRD (9%) appeared to be the cancer genes with copy number loss." (PMID 35330454, 2022). "Increasing attention has been directed toward the role of LRP1B in the field of cancer research, that being, its involvement in proliferation, metastasis, angiogenesis, and differentiation in multiple cancers." (PMID 35389768, 2022). "LRP1B is one of the most altered genes in human cancer overall and its role has been closely related to cancer progression." (PMID 35841413, 2022). "LRP1B, which encoding endocytic LDL-family receptor, is among the top 10 significantly mutated genes in human cancer." (PMID 35911687, 2022). "A total of 371 HCC patients from the TCGA dataset were involved in the study to explore the correlation between clinical characteristics, such as age, gender, prognosis, histological grade, TNM stage, cancer status, and LRP1B expression." (PMID 35389768, 2022). "LRP1B, which encodes endocytic LDL-family receptor, is among the top 10 significantly mutated genes in human cancer." (PMID 36585729, 2022). "Nevertheless, the expression status and potential functions of LRP1B in cancer are yet to be unveiled, especially in HCC." (PMID 35389768, 2022). "LRP1B inactivation is frequent in cancer and known to occur through several different mechanisms at both genetic and epigenetic levels." (PMID 34577535, 2021). "LRP1B significance as a potential therapeutic target or biomarker for cancer prognosis or response to therapy remains to be fully elucidated." (PMID 34577535, 2021). "New evidence is pushing towards the increased relevance of LRP1B in cancer as a potential target or translational prognosis and response to therapy biomarker." (PMID 34577535, 2021). "Despite LRP1B being among the most altered genes in human cancers, and the studies throughout the years supporting its role in cancer, there are still several missing links which do not allow to fully translate its relevance to the clinics." (PMID 34577535, 2021).
cancer (continued). "Since then, several studies have been trying to address the mechanisms involved in LRP1B regulation, as well as the exact role played by LRP1B in cancer." (PMID 34577535, 2021). "Over the years it was possible to confirm that LRP1B features the group of most altered genes across human cancers." (PMID 34577535, 2021). "For example, patients with LRP1B-mutant cancer showed longer progression-free survival (PFS) and overall survival (OS) than wild-type patients when treated with ICIs." (PMID 34249711, 2021). "The best polygenetic model included DIRC3_rs6759952, GAP43_rs13059137, NRG1_rs7834206, PROM1_rs72616195, LRP1B_rs1369535, and LOC100507065_rs11175834, tumorigenesis and cancer cell differentiation-related genes." (PMID 33805984, 2021). "In this study, in contrast to what is mostly reported for cancer cells, LRP1B expression is predominantly strong." (PMID 34577535, 2021). "This contributed to confirm some of the potential roles of LRP1B in cancer (addressed later on in this review)." (PMID 34577535, 2021). "Compared with wild-type LUADs, patients in the FAT3+/LRP1B+ group were correlated with earlier cancer onset (median age 63.5 vs 67 years old, p=0.012), and the tumors were more commonly occurred in Black/African American (18.18% vs 8.30%, p=0.037)." (PMID 35069585, 2021). "Taken together, several studies have demonstrated the suppressive roles of LRP1B in the cancer progression, implicating that restoring the function of LRP1B would be a promising strategy for the cancer treatment." (PMID 34386813, 2021). "Nevertheless, specific single-gene mutation analysis has been presenting as a more accessible way to predict TMB in cancer patients, with LRP1B being one of those genes." (PMID 34577535, 2021). "Intronic HPV breakpoints in FHIT and LRP1B have been related to decreased protein expression in carcinoma samples." (PMID 33810183, 2021). "The low-density lipoprotein receptor-related protein 1B (LRP1B), which encoding endocytic LDL-family receptor, is among the top 10 significantly mutated genes in human cancer." (PMID 31164891, 2019). "An investigation of a possible role of LRP1B in response to immune check-point blockade treatment in other cancer types (HNSC, ESCC, STAD, etc.)is warranted to study." (PMID 31164891, 2019). "Further elucidation of the molecular functions of the LRP1b and LRP4 ECDs has the potential to provide novel and functionally significant insights into the role of LRP1b in embryogenesis and cancer." (PMID 20383322, 2010). "Furthermore, only our quantitative-LRP-scored potential driver gene LRP1B was overlapping the known driver genes of the analyzed cancer types." (PMID 40507213, 2025). "Genes such as KIF5A, SOX10, MYL9, TRIM9, MYH11, and SNAP25 are known to play important roles in biological development, suggesting that LRP1B may also be a key factor in cancer." (PMID 40170839, 2025). "However, its function both in normal tissue and in cancer is still poorly understood and additional functional studies are needed to fully understand the connections between LRP1B, the immune system and the response to ICB." (PMID 40011914, 2025). "LDL receptor-related protein 1B (LRP1B) has been identified as a negative prognostic factor in various cancers, with its mutation status and expression levels playing a crucial role." (PMID 40170839, 2025).